RORA (RAR related orphan receptor A)
Diseases named in the same sentence as RORA in open-access papers (continued):
Sharing a sentence is not in itself a finding about the gene and the disease.
cancer (continued). "The cancer cell proliferation was reduced with the use of the REV-ERBα agonist SR9011 as well as with an RORα agonist." (PMID 37240325, 2023). "In SW480 cells, IWR1 treatment resulted in the translocation of Tet2CD from the nucleus to the cytosol, impaired TET2-induced DNA demethylation, facilitated the growth of cancer cells and decreased the expression of RORA and SPARC." (PMID 37620362, 2023). "Correspondingly, in SW620 cells, IM12 led to cytosolic-nuclear shuttling, activation of global DNA demethylation, suppression of CRC cancer cell growth and enhanced expression of RORA and SPARC." (PMID 37620362, 2023). "Of note, RORA influenced the transcript alternation of target genes and cancer growth induced by the knockdown of POU6F1, indicating the suppressive role of POU6F1/RORA in the progression of LUAD." (PMID 35504868, 2022). "Consistent with meta-analysis reports linking RORA polymorphisms to increased cancer risks, our previous TCGA data mining revealed broad downregulation of ROR gene expression in multiple cancer types." (PMID 35440077, 2022). "RORα protein levels were decreased in tumorspheres compared with levels in cells from 2D cultures, which suggests a potential function of RORα in regulating cancer cell stemness." (PMID 35605663, 2022). "As a TF, RORα binds to ROREs and modulates the transcription of genes involved in cancer cell proliferation and invasion." (PMID 36316442, 2022). "The analysis with genes as group structure highlighted 4 out of these 11 selected variables located in 4 different genes, from which RORA was detected by GMT leading to strong evidence about implication of this gene in the mechanism of both cancers." (PMID 34996381, 2022). "RORA expression was significantly lower in multiple cancer types than that in corresponding normal tissues (P < 0.05), while it was upregulated in KIRC." (PMID 35078435, 2022). "This review summarizes and discusses the current understanding of RORα function and molecular mechanisms in various pathophysiological processes, including cancer, inflammation, cerebellar development, circadian rhythm, and lipid homeostasis." (PMID 34588606, 2021). "They highlight the possible significance of manipulating RORα activity as a route towards new treatments for several diseases including cancer." (PMID 34588606, 2021). "Decreased RORα expression correlates with cancer aggressiveness, short overall survival, and poor prognosis." (PMID 34588606, 2021). "Our investigation of melatonergic genes in three independent datasets identified RORA as a cancer suppresser and prognostic marker in LIHC, consistent with some previous studies." (PMID 33842355, 2021). "The restoration of RORα expression in cancer cells suppresses cancer progression in 3D cultures and in mouse models." (PMID 34639006, 2021). "Retinoic acid-related orphan receptor α (RORα) functions as a transcription factor for various biological processes, including circadian rhythm, inflammation, cancer, and lipid metabolism." (PMID 32610705, 2020). "In this study, we propose the modulation of RORα activity as a new therapeutic strategy for cancer immunotherapy." (PMID 32610705, 2020). "As expected, the apoptosis of cancer cells was reduced when it was cocultured with CD8+ T cells treated with RORα inhibitor SR3335." (PMID 32610705, 2020). "This circadian-cancer link was confirmed in a meta-analysis showing association between risk of cancer and variants in NPAS2, RORA, RORB, and CLOCK." (PMID 31303884, 2019). "The down-regulation of RORα has been observed in a variety of cancers including breast cancer, colorectal cancer and prostate cancer." (PMID 30293994, 2018). "Consistent with our data, RORA exhibited significantly lower expression in the cancer samples from TCGA (p < 0.001)." (PMID 30293994, 2018). "RORα is commonly considered a repressor, according to investigations into its role in cancer illustrated above." (PMID 29904382, 2018).
cancer (continued). "Since RORα and RORγ are dysregulated in multiple cancer types based on published articles, they likely participate in carcinogenesis through modulating molecules such as IL-17, PRMT2, and AR or as receptors for sterols, such as vitamin D3 derivatives." (PMID 29904382, 2018). "Retinoic acid-related orphan receptor α (RORα) regulates diverse physiological processes, including inflammatory responses, lipid metabolism, circadian rhythm, and cancer biology." (PMID 28931919, 2017). "We found that the expression of RORα was reduced in gastric tissues with cancer, and this correlated with increased TNM stages." (PMID 28052040, 2017). "The retinoic acid receptor-related orphan receptor-α (RORα) is an important regulator of various biological processes, including cerebellum development, circadian rhythm and cancer." (PMID 28757615, 2017). "The genes that contributed the most to the overall association with cancer risk were NPAS2, CLOCK and RORs (RORA and RORB)." (PMID 28177907, 2017). "In support of this assumption, germline mutations or loss of function of WWOX, RORA, and PARK2 are associated with neurological diseases, whereas somatic deletions are associated with cancer." (PMID 27977694, 2016). "RORA is expressed in normal breast, prostate, and ovarian epithelium tissues but is frequently inactivated in cancers that arise from these organs." (PMID 27977694, 2016). "Our results point to RORα as a novel node in the keratinocyte differentiation network and further suggest that the identification of RORα ligands may prove useful for treating skin disorders that are associated with abnormal keratinocyte differentiation, including cancer." (PMID 23922987, 2013). "Restoration of RORα expression in cancer cells suppresses the malignant phenotypes in culture and in vivo." (PMID 23443091, 2012). "Beside its roles in the developing cerebellum, RORα has also been shown to play critical roles in many different tissues and systems, including immunity, cancer, cellular metabolism, circadian rhythm, development and ageing." (PMID 20663205, 2010). "RORa is a classical signaling pathway related to cancer, and studies involving mammals have revealed that it may be involved in regulation related to cell proliferation and apoptosis." (PMID 40370832, 2025). "The observed low IC50 values suggest these drugs may be potent tools against cancer.At the single-cell level, we found that RORA expression is significantly upregulated in CD8 + T cells within GC tissues." (PMID 40638694, 2025). "Research in cancer also shows that RORA significantly promotes autophagy levels in cancer cells." (PMID 40001602, 2025). "We first analyzed the expression of RORA across various cancer types." (PMID 40638694, 2025). "Because both RORB and its SNPs have been demonstrated to regulate cancer growth 17, 24 and because RORA levels are significantly higher in individuals with OSCC 18, RORB SNP variants may be corrected with the clinical status of OSCC." (PMID 39744492, 2025). "Interestingly, RORα has been shown to be beneficial to the stimulation of apoptosis in cancer cells." (PMID 39518891, 2024). "At the genomic level, the RORα gene is located at the middle of common fragile sites (15q22.2), large genomic regions that are highly unstable and prone to breakage and rearrangement, especially in cancer cells." (PMID 38791992, 2024). "Furthermore, animal studies and human cell line assays of cSCC reveal that RORα also inhibits cell proliferation and migration of this type of cancer." (PMID 39518891, 2024). "For example, there is research showing that clock gene variations, particularly to NPAS2, CLOCK, RORA, RORB, and PER3, may contribute to small but statistically significantly elevated cancer risk." (PMID 36387255, 2022). "Meanwhile, RORA has been extensively studied in various cancers." (PMID 35504868, 2022). "The RORA gene maps to 15q22.2, a region that is often deleted in cancer." (PMID 35605663, 2022).
cancer (continued). "These analyses uncovered a strong link between the regulation of RORA and RNASEL, both of which are associated with the immune system response and naive T cell states (they also harbor polymorphisms associated with elevated cancer risk and mortality)." (PMID 36424644, 2022). "According to our data, the dose of atorvastatin in combination with RORα/γ agonists required to achieve certain cytotoxicity in cancer cells is several to dozens of folds lower than that required for atorvastatin alone, a very exciting advantage for future application of these drugs in combination." (PMID 36316442, 2022). "Moreover, RORα plays dual roles and has a functional link between circadian rhythms and cancer pathogenesis." (PMID 34588606, 2021). "It would be interesting to determine whether the reduction of RORα in cancer cells leads to the accumulation of free complex I in the future." (PMID 34639006, 2021). "Nonetheless, RORα has important implications for pharmacological prevention of cancer, inflammation, and metabolic diseases, and understanding context-dependent RORα regulation will provide an innovative approach for unraveling the functional link between cancer metabolism and rhythm changes." (PMID 34588606, 2021). "Therefore, we further examined the roles of RORα in regulating cancer metastasis with the 4T1 model." (PMID 34639006, 2021). "The RORA gene maps to 15q22.2, a large common fragile site that is often deleted in cancer cells." (PMID 34639006, 2021). "RORA expression showed a decreased trend as the cancer AJCC stage increased." (PMID 33842355, 2021). "RORA protein product is involved in immune response, cancer and metabolism." (PMID 34512723, 2021). "The coincidence of underexpression of RORA and overexpression of RORA-negatively correlated genes might promote cell-cycle progression of cancer cells, which would further promote cancer development." (PMID 33842355, 2021). "ChIP analysis reveals that RORα acts as a transcriptional repressor of cholesterol esterification and cholesterol efflux genes by attenuating NF-κB signaling in T cells, indicating that RORα plays a key role in maintaining cholesterol homeostasis to prevent cancer progression." (PMID 32610705, 2020). "Defining this crosstalk between RORα and the Wnt/β-catenin signaling axis may contribute further approaches to improve therapeutic strategies for treating specific human cancers." (PMID 30987323, 2019). "Furthermore, gene expression profile studies in various cancers have shown that Rorα is a common down-regulated gene in certain cancer types, including breast cancer." (PMID 28931919, 2017). "As a transcription activator, RORα reduction may reduce the transcription of these tumor suppressor genes, resulting in cancer progression." (PMID 28052040, 2017). "RORA and RORB are also transcription factors which share high sequence homology, with 4% and 6% of their studied variants showing a statistically significant association with cancer risk, respectively." (PMID 28177907, 2017). "Numerous studies have provided evidence that RORα plays a role in cancer." (PMID 28931919, 2017). "Next, we investigated the downstream molecules of RORα involved in the MLN4924 anti-cancer effect." (PMID 27602774, 2016). "It was reported that RORA expression has a suppressive effect on cancer progression." (PMID 26703734, 2015). "Thus, the roles of the hypoxia-induced RORA gene product in cancer progression are currently unclear." (PMID 26703734, 2015). "NFKBIA −881G might alter the binding ability of RORα, which plays a potential role in cancer development." (PMID 22509384, 2012). "Interestingly, we found that RORα imparts some cancer-suppressive activities in the ER-negative breast cancer cell lines MDA-MB-231, MDA-MB-157 and T4-2, such as inhibition of cell migration and proliferation." (PMID 23443091, 2012). "Microarray data showed that mRNA levels of RORα are significantly reduced in many cancers." (PMID 23443091, 2012).
cancer (continued). "Treatment with SR1078 enhances apoptosis of liver cancer cells in culture, suggesting that the RORα agonist may be a potent inhibitor of cancer progression." (PMID 23443091, 2012). "Moreover, given the observed decline in the expression of CYP27B1, VDR, CYP11A1, and RORα/γ during cancer progression, as previously discussed, the utility of VD-based treatments may be confined to early rather than advanced stages of the disease." (PMID 38689243, 2024). "However, reports about the role of RORA in cancer drug resistance have been rarely seen." (PMID 38560570, 2024). "Moreover, recent studies demonstrated that RORα is involved in tumorigenesis, suggesting that RORα may be considered a potential therapeutic target in many cancers." (PMID 32120841, 2020). "Finally, we assessed whether the reprogrammed cholesterol metabolism of CD8+ T cells by either RORα inhibition or activation controls cancer progression in vitro." (PMID 32610705, 2020). "Four members of the retinoic acid-related orphan receptor α (RORα) family (RORα1, RORα2, RORα3 and RORα4) are transcription factors that regulate several processes including circadian rhythm, lipid metabolism, cerebellar development, immune function, and cancer." (PMID 30987323, 2019). "RORα-targeted therapeutics may efficiently suppress certain types of tumors, thus it is crucial to identify potent ligands or agonists that have the potential to be used in cancer treatment." (PMID 23443091, 2012). "Additionally, RORα is expressed at very low levels in many cancers suggesting that low RORα expression may be one mechanism underlying tumorigenesis." (PMID 22509368, 2012). "In cancer research, overexpression of the MYCN gene disrupts circadian rhythms and inhibits RORA expression." (PMID 40001602, 2025). "It appeared in different cancer datasets, specifically in THB (P10828), VDR (P11473), NR1D1 (P20393), and RORA (P35398)." (PMID 40334012, 2025). "Among 7912 samples across 18 cancer types, we interestingly observed that the majority of the clock control gene, such as HLF, KLF10, FBXL3, TEF, RORs (RORA, RORB, RORC), and NR1D2, are down-regulated in a wide range of cancers." (PMID 36895015, 2023). "Furthermore, specific clock genes REV-ERBα and RORα deficient mice have negative effects on the development of and activation of dendritic cell and other antigen presenting cells critical to pathways involved with immune-mediated cancer cell targeting." (PMID 38090501, 2023). "As TIMELESS expression was significantly upregulated and RORA, PER1, PER2, and CRY2 expression was significantly downregulated in most cancer types including LUAD and LUSC, it is necessary to probe their prognostic values." (PMID 35078435, 2022). "RORA was significantly underexpressed in eight cancer types but was overexpressed in KIRC, whereas CYP1A1 was underexpressed in seven cancer types but was overexpressed in COAD." (PMID 33842355, 2021). "Multivariate Cox regression analysis revealed that RORA was an independent prognostic factor in the TCGA-LIHC dataset after controlling for AFP, cancer size, and TNM stage." (PMID 33842355, 2021). "Gene sets based on aryl hydrocarbon receptor signaling, RORA activates gene expression, and RARRXR pathway identified in our study are related to gene regulation and consequently have a role in cancer." (PMID 32583859, 2020). "Whereas there are nine rhythm genes (MTNR1B, NR1D1, RORB, RORA, OPN4, C1orf51, PROK2, SERPINE, and EGR3) that are differently expressed in the high and low MSI group in more than 1/3 cancer types." (PMID 31927791, 2020). "However, the mechanism of RORα down-regulation in cancers remains unclear." (PMID 30293994, 2018).
cancer (continued). "We demonstrated that in vitro and in vivo cancer cells after PER1 knockdown, PER2, DEC1, DEC2, CRY1, CRY2 and NPAS2 were significantly down-regulated at the mRNA level, while PER3, TIM, RORα and REV-ERBα were significantly up-regulated." (PMID 27602964, 2016). "Thirty proteins, excluding RORA, XPC and ERCC2, are known to play important roles in the expression of malignant phenotypes involved in cancer initiation and/or progression, such as increased invasion, aberrant metabolism and enhanced survival." (PMID 26703734, 2015). "Unlike RORγ, RORα was found to be downregulated in several cancer types, including breast, ovarian, and prostate cancer." (PMID 35246220, 2022). "Regarding RORA, the upregulated clusters in KEGG pathways were complicated, including many cancers and signaling pathways (e.g., Wnt signaling pathway, PI3K-Akt signaling pathway, Hedgehog signaling pathway; Fig. 5B1), while the upregulated GO clusters were enriched in embryonic development." (PMID 35078435, 2022). "In addition, it was shown that Cluster 1 (CRY2, PER1, and RORA) and TIMELESS exerted opposite impacts on interactive gene network, infiltration of immune cells, cancer-related signaling pathways, and cellular sensitivity to clinically used drugs." (PMID 34745328, 2021). "Besides, CRY2, PER1, and RORA exerted opposite impacts against TIMELESS on immune cell infiltration and cancer-related signaling pathways, affecting the overall survival of HCC patients." (PMID 34745328, 2021). "Although RORα is a very promising target that can be applied to circadian rhythm, cancer, and metabolic and immune diseases, there are no drugs precisely targeting RORα on the market." (PMID 34588606, 2021). "Interestingly, NR3C2, PGR, RORA were differentially expressed in all 16 cancer types, while HNF4G was differentially expressed in only 5/16 cancers (31.3%)." (PMID 32024906, 2020). "RORα, a member of the orphan nuclear receptor (ONR) family, plays an essential role in various physiological functions such as cellular differentiation, metabolic pathway, inflammation, and cancer." (PMID 32610705, 2020). "However, CD8+ T cells with RORα activation by CS enhanced the effector responses of CD8+ T cells, thereby inhibiting the viability of cancer." (PMID 32610705, 2020). "In order to achieve a systematic understanding of circadian clock in cancer, we define a core subset of clock family genes including 7 positive regulators (CLOCK, NPAS2, ARNTL, ARNTL2, RORA, RORB, and RORC) and 7 negative regulators (PER1, PER2, PER3, CRY1, CRY2, NR1D1, and NR1D2)." (PMID 31708917, 2019). "As discussed in this review, the protumor or antitumor effects of RORα and RORβ in cancer have not been intensively explored, requiring further study and evidence." (PMID 29904382, 2018). "This study demonstrates that the down-regulation of PER1 in cancer cells can result in the robust up-regulation of PER3, TIM, RORα and REV-ERBα transcripts, while the expression of PER2, DEC1, DEC2, CRY1, CRY2 and NPAS2 is prominently down-regulated in vitro and in vivo." (PMID 27602964, 2016). "Quantitative real-time PCR result indicated that in vitro and in vivo cancer cells after PER1 knockdown, PER2, DEC1, DEC2, CRY1, CRY2 and NPAS2 were significantly down-regulated at the mRNA level, while PER3, TIM, RORα and REV-ERBα were significantly up-regulated." (PMID 27602964, 2016). "RORα activates nuclear receptor pathways in cancer cells that can be categorized as canonical and non-canonical." (PMID 23443091, 2012). "The MAF oncogene, HOP, RORA and EGR3 from the same cluster directly participate in the regulation of growth, and as a consequence may be better markers of cancer differentiation status." (PMID 19888454, 2009).